SUZ12 (SUZ12 polycomb repressive complex 2 subunit)
Diseases named in the same sentence as SUZ12 in open-access papers (continued):
Sharing a sentence is not in itself a finding about the gene and the disease.
tumor (continued). "The CD44hi cells from the M-1 tumor exhibited a more primitive phenotype (in terms of expected BMI, hTERT, SUZ12, EZH2, OCT-4 expression), as compared to the CD44hi cells from the M-2 sample (with only higher hTERT expression)." (PMID 24019906, 2013). "We examined the significant genes from Ectoderm (FDR < 0.0003 in 5 tumor types) and Epidermis development (FDR < 7.7×10-5 in 5 tumor types) in each cancer type in the context of the occupancy of PRC2 components SUZ12 and EED, and H3K27me3." (PMID 23033966, 2012). "A good candidate for such a modifier gene influencing tumour development is SUZ12 which is located within the 1.4-Mb NF1 microdeletion region." (PMID 23101500, 2012). "The copy number profile observed in ccfDNA mirrored that of the tumor, showing large chromosomal gains (1q, 7p, 8q, 9q, and 17q) and losses (6p and 9p), as well as focal deletions in the CDKN2A, SUZ12, and SMARCA2 genes associated with the transition from PN to ANNUBP." (PMID 41463204, 2025). "Notably, recent studies have linked the inactivation of Polycomb Repressive Complex 2 (PRC2), which contains SUZ12 as a core subunit, to enhanced anti-tumor cytotoxicity of DAC through retroelement reactivation and the associated inflammatory response." (PMID 39930152, 2025). "However, the protein expression of SUZ12 in HCC tissues was lower than that in adjacent para-tumor tissues." (PMID 39530087, 2024). "Our study showed that SUZ12 led to marked upregulation of PD‐L1 protein expression, which may be related to tumor immune escape." (PMID 39400513, 2024). "SUZ12 has a pivotal role in promotion of tumor cell proliferation and metastasis." (PMID 37807067, 2023). "Furthermore, the study conducted siRNA-mediated knockdown experiments of SUZ12, which demonstrated a noteworthy inhibition of tumor cell growth, migration, and invasion." (PMID 37909018, 2023). "Interestingly, the mean H-Score for EZH1 was significantly higher in P-NEN compared to GEP-NEN but similar for all tumor grades, while SUZ12 and EED were barely expressed across all grades and entities." (PMID 35740494, 2022). "Moreover, integration with ENCODE data revealed that proximal tumor-gained promoters were associated with EZH2 and SUZ12 occupancies, which are the core components of PRC2 (polycomb repressive complex 2)." (PMID 33916417, 2021). "Furthermore, we and others have found that SUZ12 promotes tumor cell epithelial-to-mesenchymal transition (EMT), which presents the critical function in the metastatic development of human carcinomas." (PMID 34167089, 2021). "Moreover, SUZ12 knock- down induces impaired tumor growth, invasion and metastasis in bladder, gastric and colorectal cancers." (PMID 34167089, 2021). "Hypermethylated promoter regions in ALK tumor cells showed strong enrichment of binding sites for proteins associated with chromatin remodeling in ESC, in particular PRC associated proteins including CBX7, EZH2, MTF2, PHF19, RING1B, RNF2, and SUZ12." (PMID 33310759, 2021). "Interestingly, integration with ENCODE data revealed that proximal tumor-gained promoters were associated with EZH2 and SUZ12 occupancies, which are the core components of polycomb repressive complex 2 (PRC2)." (PMID 33916417, 2021). "Furthermore, we observed the association between proximal tumor-gained promoters with EZH2 and SUZ12 occupancies." (PMID 33916417, 2021). "To determine whether the additional tumor types were consistent with those observed in human patients, we examined the SUZ12 mutant sample cohort of the AACR Genie database." (PMID 32651197, 2020).
tumor (continued). "It has previously been described in the murine system that Suz12 acts as a tumor suppressor in Nf1-deficient but not in Nf1-wild-type tumors." (PMID 32651197, 2020). "Because of the low incidence of multifocal tumors in the nf1a+/+ cohort, loss of suz12 did not significantly affect tumor onset." (PMID 32651197, 2020). "In summary, we show that the role of PRC2 in tumor suppression is very sensitive to the dosage of suz12 in multiple tissues and that complete loss of suz12 is not required to promote tumorigenesis." (PMID 32651197, 2020). "Transition from the benign to malignant state also coincides with rise of genomic instability, which likely accelerates loss of function of key tumor suppressors (e.g. EED, SUZ12) and affects copy-number status of multiple oncogenes and other tumor suppressor genes." (PMID 32642732, 2020). "Indeed, suz12 (a core component of the polycomb repressive complex 2) knockdown inhibits tumour metastasis in vivo via MALAT1." (PMID 31382922, 2019). "Moreover, SUZ12 induced tumor cell epithelial-to-mesenchymal transition (EMT) and maintained the invasive potential of cancer, which appeared to play a crucial role in the metastatic progression of human carcinomas." (PMID 31234902, 2019). "Additionally, the expression levels of both SUZ12 and KRAS were pronouncedly higher in metastatic tissues than in primary tumor tissues, suggesting the functions of SUZ12 and KRAS were also closely metastasis related." (PMID 30791232, 2019). "Together, these findings revealed that SUZ12 knock‐down impaired tumour growth of HNSCC in vivo, suggesting that SUZ12 might be required for HNSCC growth." (PMID 29667751, 2018). "Moreover, SUZ12 mRNA is significantly overexpressed in TCGA‐HNSCC samples as compared to non‐tumour samples (44 cases)." (PMID 29667751, 2018). "Moreover, the number of Ki67‐positive cells was significantly reduced in tumour samples from SUZ12 knock‐down cells as compared to samples formed from control cells." (PMID 29667751, 2018). "Swine also harbor the Polycomb Repressive Complex 2 Subunit(SUZ12) gene, which is recurrently inactivated in NF1-associated malignancies and could be mutated or deleted with NF1 to drive the formation of additional tumor types." (PMID 30302402, 2018). "Moreover, targeting SUZ12 by gene knockdown suppresses the migratory and invasive properties of cancer cells and inhibits tumor metastasis in animal models." (PMID 28228691, 2017). "While short-term exposure to high concentrations of PEITC (6–12 μM for 48 h) was sufficient to reduce tumor cell expression of BMI-1, marked decreases in the expression of key PcG complex proteins SUZ12 and EZH2 were only observed after long-term treatment (2.5 μM PEITC for 6 weeks)." (PMID 28079155, 2017). "Finally, to assess the clinical significance and prognostic value of tumor budding, miR-320a and Suz12 in TSCC patients, we performed ISH and IHC in another patient cohort with 100 TSCC patients." (PMID 27582550, 2016). "Furthermore, we found that high intensity of tumor budding, decreased expression of miR-320a and increased expression of Suz12 in TSCC were strong predictors of decreased overall survival." (PMID 27582550, 2016).
tumor (continued). "We concluded that decreased expression of miR-320a could promote invasion and metastasis of tumor budding cells by targeting Suz12 in TSCC." (PMID 27582550, 2016). "SUZ12 is critical for tumor pathogenesis and development, and may be involved in the regulation of tumor stem cells." (PMID 25295075, 2014). "Interestingly, recent data concerning biomolecular characteristics of GS documented that, although GS has a genetic profile that overlaps with GBM and other neoplasms, it is also true that GS has its genetic mutations, such as MSH6, BRAF, SUZ12, SOX2, and FBXW7." (PMID 38202090, 2023). "Haploinsufficiency of certain genes may contribute to dysmorphic facial features, overgrowth and reduced cognitive capability (RNF135) or heart defects (ADAP2), whereas others might have tumor suppressive function, thus their deletion promote tumor development (SUZ12, ATAD5)." (PMID 34168676, 2021). "By association with the other PRC2 component protein SUZ12, MALAT1 decreases E-cadherin expression and increases N-cadherin and fibronectin expression, leading to epithelial mesenchymal transition (EMT), bladder cancer cell migration, and invasion in vitro and tumor metastasis in animal models." (PMID 32174966, 2020). "Thus, through its effect on SUZ12, one may speculate that miR‐367 in cancer cells might help sustain expression of pluripotency genes known to enhance tumor cell stemness and aggressiveness." (PMID 31402560, 2019). "In addition to the deletion of SUZ12 and ATAD5, hemizygosity forthe genes COPRS, UTP6 and RNF135 may alsocontribute to the increased tumour risk associated with NF1 microdeletions." (PMID 28213670, 2017). "To further investigate whether this upregulation of p16INK4a was reflecting changes in the transcription levels of known regulators of this tumor suppressor, such as Bmi1 15,25, Ezh1 26, Ezh2 27,28, and Suz12 29, we analyzed the expression of these genes by qPCR." (PMID 24307508, 2014). "Elevation of SUZ12 was histologically inconsistent, whereas EED expression was observed across tumor subtypes, as well as in normal liver." (PMID 40766612, 2025). "When specificially examining the tumor samples alone, we found that the cycling HepT population expressed high levels of EZH2, SUZ12, and EED, along with cell cycle regulators MKI67, AURKB, ASPM, TOP2A, and HELLS." (PMID 40766612, 2025). "The seven genes comprising the HMR model (SUZ12, KAT2A, AURKA, BUB1, SUV39H2, UTY, and PCGF5) are critically involved in epigenetic modification, tumor progression, supporting their prognostic value in MM." (PMID 40949882, 2025). "When comparing tumor and adjacent non-tumor prostate tissues, we found that DNA hypermethylated regions are enriched for PRC2/H3K27me3 pathways and EZH2/SUZ12 cofactors." (PMID 38566104, 2024). "In view of our findings indicating the activation of STAT3 signaling pathway through the degradation of SUZ12 and EZH2 mediated by SUMOylated HSPA9, we investigated the role of STAT3 in MUL1-induced tumor inhibition effects." (PMID 39113711, 2024). "Immunohistochemical staining and Western blotting were used to observe the expression of risk model factors PRR11, KIF11, RACGAP1 as well as the potential common transcription factors YY1, CREB1 and SUZ12 in HCC tissues and para-tumor tissues." (PMID 39530087, 2024). "Overexpression of SUZ12 and EED protein was also detected in KIRC tumor tissues, albeit to a lesser extent than in LIHC." (PMID 39516467, 2024). "The tumor growth was significantly suppressed by KD of EZH2, SUZ12, or integrin α11 which was given to the cells at initial implantation." (PMID 38664825, 2024). "Previously, EZH2, SUZ12, EED, MTF2 and JARID2 have all been suggested to not only act as oncogenes, but also to have tumor suppressor activities, depending on the type of cancer." (PMID 38562687, 2024). "SUZ12 is an oncogene of NSCLC, and its knockdown inhibits tumor cell growth, migration, and invasion." (PMID 37909018, 2023).
tumor (continued). "SUZ12, as a main constituent of Polycomb repressive complex 2 (PRC2), is related to the invasion, metastasis, proliferation, and apoptosis inhibition of tumor cells." (PMID 37636389, 2023). "Contrary to expectations, the deletion of EZH2 and SUZ12 in both mouse and human GR3 MB via TALEN and CRISPR-Cas9 gene editing is able to accelerate the tumor progression, suggesting a tumor suppressor activity of the protein complex in the tumor." (PMID 36968588, 2023). "The knockdown of SUZ12 significantly inhibited cell proliferation, invasion, and migration in HNSCC cells and inhibited xenograft tumor growth." (PMID 36076977, 2022). "Our Gene Ontology enrichment analysis suggests that the tumor-gained H3K4me3 regions exhibiting EZH2 and SUZ12 are enriched with genes related to development processes." (PMID 33916417, 2021). "Here, we performed a comprehensive analysis of data in the genomic and transcriptomic (cBioPortal, KMplot) database portals of clinical tumor samples and evaluated clinical correlations of EZH2, SUZ12, and EED." (PMID 34202528, 2021). "The analysis of cBioPortal clinical data indicates that amplification of EZH2, SUZ12, and EED genes was not limited to one particular malignancy but varied between different tumor types." (PMID 34202528, 2021). "Proximal tumor-gained promoters (‘gained.TSS’ regions) significantly enriched with EZH2 (p-value < 1.6 × 10–16, Fisher’s exact test) and SUZ12 (p-value < 3.5 × 10–15, Fisher’s exact test) binding sites." (PMID 33916417, 2021). "In total, in 10 tumor types, the higher expression of at least one of the EZH2, SUZ12, or EED genes was significantly correlated with poor prognosis (logrank p < 0.05)." (PMID 34202528, 2021). "The high EZH2, SUZ12, and EED expression in tumor samples has been attributed to the decreased patient survival in several tumor types." (PMID 34202528, 2021). "Given the importance of PRC2 as a histone methyltransferase in HCC, we further investigated the interaction between CRNDE and EZH2, SUZ12, and SUV39H1, and found that the inhibitory effect of EZH2, SUZ12, and SUV39H1 on tumor suppressors was mediated by CRNDE." (PMID 32826865, 2020). "After LINC00659 inhibition, the protein levels of SUZ12, p21, Cyclin E, Cyclin D and CDK2 in SGC‐7901 tumour tissue were significantly higher than those of SGC‐7901‐LINC00659−/−." (PMID 33145980, 2020). "It appears that at least in NF1-associated MPNSTs, progression from benign to malignant status frequently proceeds through sequential inactivation of three tumor suppressors: NF1, CDKN2A/B, and SUZ12 and/or EED (PRC2 complex)." (PMID 32642732, 2020). "Next, we investigated the impact of CRNDE on several tumor suppressor genes that are reported to be inhibited by EZH2, SUZ12, and SUV39H1-mediated histone trimethylation." (PMID 32826865, 2020). "In the present study, we investigated the molecular mechanisms through which LINC01234 regulated the tumor progression-related behavior of NSCLC cells, and found that LINC01234 interacted with several RNA-binding proteins, including Ago2, EZH2, LSD1 and SUZ12." (PMID 31959200, 2020). "PRC2 is recognized as important and context-dependent tumor suppressive or oncogenic molecule, and its subunits EZH2 and SUZ12 were reported to inhibit the the expression of numerous tumor suppressor genes by influencing H3K9me and H3K27me3 levels." (PMID 32826865, 2020). "Collectively, miR‐487b is regulated by DNA methylation and it functions as a tumor suppressor in CRC mainly through targeting MYC, SUZ12, and KRAS." (PMID 30791232, 2019). "The expression levels of three most silenced TSGs as well as p16 were analyzed in two H3.3K27M mutant tumor cells (SF7761 and SF8628) after depletion of Suz12." (PMID 29932419, 2018). "The frequencies of cases showing high expression, which was defined as positive expression in>75% of tumor cells, were 55.2% (91/167) for EZH2, 32.3% (54/167) for SUZ12, 37.1% (62/167) for H3K27me3, and 31.1% (52/167) for BMI1." (PMID 28412742, 2017).
tumor (continued). "A strong inverse correlation was also observed between miR-320a and Suz12 as determined by IHC and ISH in xenograft tumor samples." (PMID 27582550, 2016). "Tumor-specific mRNA transcript for predicted protein contains 5-prime end of the JAZF1 and 3-prime end of the SUZ12 sequence, with retaining zinc finger motifs from both genes." (PMID 26879382, 2016). "Markers that characterize candidate CSC (hTERT, SUZ12, OCT-4 expression etc.)are evident in cell pellets isolated from the MPE samples; thus, CSC are a likely component of the MPE-tumor mix." (PMID 24019906, 2013). "ANRIL directly binds to the SUZ12 protein, an essential component of polycomb repressive complex 2, and is required for SUZ12 occupancy of the CDKN2A/CDKN2B tumour suppressor genes as well as for their epigenetic silencing." (PMID 23101500, 2012). "Additionally, we performed immunohistochemical staining of EZH2, EED, SUZ12, and H3K27me3 on archived UTUC tumor tissues to reveal the presence of PRC2." (PMID 36428492, 2022). "In addition, we wanted to obtain more insight by examining those genes whose TSSs exhibited tumor-gained H3K4me3 signals and EZH2/SUZ12 TFBS." (PMID 33916417, 2021). "In addition, a network of EZH2 and its interacting proteins (UBC, CDK1, HDAC1, SUZ12, EED) was found to participate in miR-26a-mediated tumor progression." (PMID 34381816, 2021). "miR-204-5p is a tumor suppressor in HNSCCs, which inhibits tumor growth, metastasis, and stemness by suppressing the signal transducer and activator of transcription 3 (STAT3) signaling and EMT via targeting SNAI2, SUZ12, HDAC1, and JAK2." (PMID 33917482, 2021). "These inhibitors attenuated tumor growth, with AZD2014 exerting the most significant effects and also reduced mTORC1 activation (as assessed by EIF4EBP1 phosphorylation) and the expression of EZH2 and SUZ12 proteins." (PMID 31263101, 2019). "Notably, MYC, SUZ12, and KRAS can also be suppressed by 5‐Aza in other manners, especially with the involvement of miRNAs in different tumor microenvironments." (PMID 30791232, 2019). "Furthermore, shRNA‐mediated SUZ12 knock‐down significantly inhibited cell proliferation, migration and invasion in HNSCC cells, and resulted in compromised tumour growth in vivo." (PMID 29667751, 2018). "Moreover, the expression of SUZ12 protein was also determined in 20 pairs of HNSCC samples and adjacent non‐tumour tissue." (PMID 29667751, 2018). "Furthermore, miR-200c functions as a tumor suppressor by directly inhibiting PRC oncogenes, Bmi1 and Suz12." (PMID 26930714, 2016). "Suz12 was predominantly located in the nucleus and was upregulated in the central tumor and TIF; thus it showed a negative correlation with miR-320a in the TSCC slices." (PMID 27582550, 2016). "Additionally, we report a progressive increase in EZH2/PRC2 activity in PTC, as evidenced by increased EZH2 and SUZ12 expression in tumor tissue compared to adjacent nontumoral tissue in the TCGA database." (PMID 37175580, 2023). "The PRC2 complex is composed of several subunits (EZH2, EED, SUZ12, JARID2 and Rbap46.48), which are often amplified in MB, and their actions leads to an elevated level of H3K27me3 by repressing specific tumor suppressor genes, thus facilitating tumor development." (PMID 36968588, 2023). "SUZ12 positive staining was identified mainly in nucleus and scarcely in cytoplasm in HNSCC, whereas negative or weak staining was detected in the normal counterparts (20 oral mucosae obtained from non‐tumour surgery and histologically verified) as well as tumour stroma in HNSCC samples." (PMID 29667751, 2018). "Not all type 2 microdeletions can be PCR amplified by a primer set for common breakpoints, and thus we cannot rule out the involvement of NF1-REPs or the SUZ12 sequences in the deletion identified in tumor P004-7N, because MLPA results were consistent with this type of deletion." (PMID 21031597, 2011).